INS (insulin)
Diseases named in the same sentence as INS in open-access papers (continued):
Sharing a sentence is not in itself a finding about the gene and the disease.
diabetes (continued). "Type 1 diabetes mellitus (T1DM) is caused by cellular-mediated autoimmune destruction of pancreatic islet beta-cells leading to loss of insulin production." (PMID 20634940, 2010). "While the majority of current diabetes treatments focus on reducing blood glucose levels, hypoglycemia represents a significant risk associated with insulin treatment." (PMID 20418955, 2010). "Understanding the biochemical networks that underlie metabolic homeostasis and how they associate with insulin action will help unravel diabetes etiology and should foster discovery of new biomarkers of disease risk and severity." (PMID 21170321, 2010). "Insulin and sulfonylurea therapy for diabetes mellitus carries the risk of hypoglycaemic brain injury, and this risk is a major impediment to optimal glucose regulation in diabetic patients." (PMID 20513244, 2010). "Diabetes is a devastating disease that is ultimately caused by the malfunction or loss of insulin-producing pancreatic beta-cells." (PMID 20886041, 2010). "Although interventions that reduce inflammatory parameters have been associated with improved insulin and glucose metabolism during insulin resistance and type 2 diabetes, the mechanisms connecting inflammation and diabetes are still unclear." (PMID 20948968, 2010). "We find that following exposure to T, or the selective AR-agonist dehydrotestosterone (DHT), CF mice challenged with STZ, which are normally protected, are prone to β-cell failure and insulin-deficient diabetes." (PMID 20585581, 2010). "A number of animal models of diabetes develop neuropathy, but in different ways, depending on the background strain, diet composition, insulin/C-peptide deficiency, coexisting hyperglycemia and hypertension and duration of diabetes." (PMID 20871761, 2010). "Diabetes mellitus is a chronic syndrome of impaired carbohydrate, protein, and fat metabolism caused by insufficient secretion of insulin and/or defects in insulin action in tissues due to insulin resistance." (PMID 20508722, 2010). "Our present data indicate that there is a close link between insulin deficient diabetes and cerebral amyloidosis in the pathogenesis of AD." (PMID 21044348, 2010). "In the present study we have endeavored to understand the molecular basis for the onset of insulin deficiency in the syndrome of Mutant INS-gene-induced Diabetes of Youth (MIDY)." (PMID 20948967, 2010). "In animal models of diabetes, impairments of spatial learning occur in association with distinct changes in hippocampal synaptic plasticity due to defects in insulin action in the brain." (PMID 20868513, 2010). "The homeostasis model assessment approach takes into the consideration the interactions between glucose and insulin via the specialized cell populations and thereby increases diagnostic power in diabetes." (PMID 21152006, 2010). "Conversely, CF mice exposed to T or DHT became vulnerable to STZ and showed a severe predisposition to insulin-deficient diabetes." (PMID 20585581, 2010). "Diabetes and insulin resistance are associated with endothelial dysfunction as well as reduced insulin sensitivity of the endothelium - reduced insulin-stimulated endothelial function." (PMID 20500877, 2010). "They tested a panel of 58 biomarkers in 160 cases and 472 controls and found that six biomarkers (adiponectin, CRP, ferritin, interleukin-2 receptor A, glucose and insulin) helped to predict the 5-year risk of incident diabetes." (PMID 20396381, 2010). "Previous studies have shown that ER stress-mediated apoptosis and CHOP-mediated apoptosis are involved in the pathogenesis of hereditary diabetes mellitus in mice caused by a point mutation in the insulin gene, and ischemia-induced neuronal cell death in vivo." (PMID 20148646, 2010).
diabetes (continued). "Taken together, telomerase deficiency and hence short telomeres impair replicative capacity of pancreatic beta-cells to cause impaired insulin secretion and glucose intolerance, mechanistically defining diabetes mellitus as an aging-associated disorder." (PMID 20876939, 2010). "More recent are numerous reports of insulin-deficient diabetes caused by heterozygous mutations in the insulin gene." (PMID 20948967, 2010). "Higher age, low socioeconomic status, treatment with insulin, longer duration of diabetes and poor glycemic control were risk factors for DPN." (PMID 20431800, 2010). "We observed that, both in normal condition and following T exposure, Tfm mice were protected against STZ-induced insulin deficient diabetes." (PMID 20585581, 2010). "Measuring insulin changes in response to changes in glucose provide the basis for partitioning alterations in system response (i.e., diabetes) into deficiencies in insulin production (i.e., type 1 diabetes) and insulin action (i.e., type 2 diabetes)." (PMID 20843320, 2010). "Assuming an additive genetic model the diabetes-associated major C-allele of rs4607103 near ADAMTS9 associated with reduced insulin-stimulated glucose uptake (p = 0.002) during a hyperinsulinemic euglycemic clamp." (PMID 19789630, 2009). "There is a strong association between visceral adiposity and insulin resistance patterns of glucose homeostasis, including in type 2 diabetes mellitus." (PMID 19696902, 2009). "Diabetes is characterized by reduced insulin-mediated glucose uptake associated with reduced GLUT4 expression." (PMID 19607676, 2009). "Neurodegenerative diseases affect a major proportion of the general population and 20% of them are associated with diabetes mellitus, increased insulin resistance and obesity, disturbed insulin sensitivity, and excessive or impaired insulin secretion." (PMID 27713238, 2009). "Association between maternal insulin sensitivity and the incidence of type 2 diabetes mellitus in low birth weight babies is confounded by many factors and hence, has limited value in the determination of any genetic origin of the disease." (PMID 20062558, 2009). "After controlled for physical performance, chronic conditions, cardiovascular covariates, and use of sedatives or anxiolytics, the association between non-insulin-treated diabetes and falls was significantly attenuated (RR, 1.18 [CI, 0.87 to 1.60])." (PMID 19127292, 2009). "Conclusively, the p38δ-PKD pathway modulates both insulin secretion and β cell turnover and thus provides a unifying mechanism that integrates these two pathogenic features of human diabetes." (PMID 19135240, 2009). "UK type 2 diabetes patients are at increased risk of a large number of diabetes-related complications due to an unnecessary delay in insulin initiation." (PMID 19804622, 2009). "Our analysis showed that a first barrier to successful diabetes care was GPs inadequate knowledge how to manage insulin therapy and cardiovascular risk." (PMID 19624848, 2009). "Dysfunction and loss of insulin-producing pancreatic β cells represent hallmarks of diabetes mellitus." (PMID 19135240, 2009). "Diabetes is a chronic disease that results from deficiency in insulin production or the presence of ineffective insulin." (PMID 22454583, 2009). "Significant risk factors for DR were: male sex, long duration of diabetes, oral medication or insulin use, presence of systemic hypertension and nephropathy." (PMID 19835608, 2009). "All of this added to the risk for clinical inertia for diabetes intensification and the initiation of insulin." (PMID 19426530, 2009). "Several metabolic complications, accompanied by insulin deficiency or impaired insulin responsiveness and calcium handling abnormalities, are common to both types 1 and 2 diabetes." (PMID 19649297, 2009). "The potential roles of MPP7 mutations in diabetes and perturbed islet cell polarity in insulin secretion warrant further study." (PMID 19216786, 2009).
diabetes (continued). "Body weight loss and hyperglycemia induced by diabetes were markedly restored by insulin treatment of 5 days." (PMID 19706162, 2009). "Gastric bypass surgery results in significant metabolic changes associated with weight loss, improved insulin sensitivity and glucose homeostasis, and a reduction in co-morbidities such as diabetes and coronary heart disease." (PMID 19936240, 2009). "In this study we explored the role of NEP in neuropathy related to either insulin-deficient diabetes or diet-induced obesity using NEP deficient (−/−) mice." (PMID 20148083, 2009). "Roux-en-Y gastric bypass (RYGB) surgery is associated with weight loss, improved insulin sensitivity and glucose homeostasis, and a reduction in co-morbidities such as diabetes and coronary heart disease." (PMID 19936240, 2009). "Reduced insulin secretory capacity and loss of mass of the pancreatic β-cells are hallmarks in the development of type 2 diabetes mellitus (T2DM)." (PMID 19607692, 2009). "Protein coded by PTPN1, a tyrosine phosphatase kinase gene is a negative regulator of insulin signalling and has been reported to be associated with diabetes mellitus." (PMID 19997558, 2009). "Both of these clinical outcomes are driven by substantial reductions in the cumulative incidence and time to onset of most diabetes-related complications due to the improvements in glycaemic control associated with insulin administration." (PMID 19804622, 2009). "Glucose dysregulation, including elevated plasma glucose, increased hepatic gluconeogenesis, and decreased insulin mediated glucose transport, is a hallmark of type 2 diabetes mellitus (T2DM)." (PMID 19092995, 2008). "For example, most INS mutations are believed to cause diabetes due to a loss of beta-cell function and mass, that is the result of the mutant dominant-negative acting INS allele." (PMID 19787084, 2008). "The variables that showed significant differences by χ2 test and unpaired Student t test (insulin therapy, diabetes duration, age of diabetes onset) plus the VEGF polymorphism were analyzed together in a logistic regression analysis." (PMID 18682813, 2008). "Certainly, resistance to the actionsof insulin is strongly associated with CVD in patients with diabetes." (PMID 18288280, 2008). "Since 1920s, insulin therapy has changed diabetes from a rapidly fatal disease to a chronic disease associated with significant secondary complications, such as renal failure, cardiovascular disease, retinopathy and neuropathy." (PMID 18298656, 2008). "The primary cause of hypoglycaemia in Type 2 diabetes is diabetes medication—in particular, those which raise insulin levels independently of blood glucose, such as sulphonylureas (SUs) and exogenous insulin." (PMID 18215172, 2008). "Diabetes develops from either deficiency in insulin production or an impaired utilization of insulin." (PMID 20142938, 2008). "Skeletal muscle accounts for the majority of insulin-stimulated glucose disposal, and defects in muscle insulin action represent an early marker for diabetes risk." (PMID 19011679, 2008). "Diabetes is either type 1, as a result of frank deficiency of insulin or type 2, due to resistance of tissue to respond insulin." (PMID 20046733, 2008). "These metabolic abnormalities result, in part, from a deficiency of the blood sugar-lowering hormone insulin; this deficiency in insulin results in type 1 diabetes or insulin-dependent diabetes mellitus (IDDM)." (PMID 21264155, 2008). "In summary, the fundamental characteristic of Type 1 diabetes mellitus is the loss of endogenous insulin production." (PMID 18167535, 2008). "In the Insulin resistance Atherosclerosis study (IRAS), both high ALT and AST were associated with incident diabetes after adjustment for full range of diabetes risk factors in addition to the markers of insulin sensitivity." (PMID 18533046, 2008).
diabetes (continued). "Chemically (STZ)-induced diabetes has been shown to produce a partial or total deficiency of insulin that causes decrease in the concentration of glycolytic enzymes." (PMID 19902032, 2008). "In the logistic regression model (diabetes duration, age of diabetes onset, incidence of insulin therapy, and the VEGF polymorphism) the CC genotype of the VEGF polymorphism was not an independent risk factor for PDR." (PMID 18682813, 2008). "Some of these factors are interrelated, as increasing diabetes duration is inevitably associated with increasing age and increasing loss of endogenous insulin secretion." (PMID 18215172, 2008). "Type 2 diabetes or non-insulin-dependant diabetes mellitus (NIDDM) is a result of hyperglycemia caused by overproduction of glucose at the hepatic level or because of abnormal β cell function or insulin resistance at target cells." (PMID 21264155, 2008). "Therapeutic/physiological factors associated with increased risk include older age, duration of diabetes, presence of comorbidities, renal impairment, loss of residual insulin secretion, defective counterregulation and loss of awareness of hypoglycaemia." (PMID 18215172, 2008). "Diabetic retinopathy was associated with type 2 diabetes, diabetes duration >10 years, use of oral anti-diabetic agents, use of insulin, HbA1c above 7%, unstable blood glucose levels and the use of anti-hypertensive medication." (PMID 18655733, 2008). "Regarding the essential role played by glucose and insulin on immune cells, variations in their levels which occur in diabetes are most likely involved in immunedisorders associated with this trait." (PMID 18350123, 2008). "Traditionally regarded as a drastic measure in Type 2 diabetes, physicians are increasingly favouring earlier introduction of basal insulin to control hyperglycaemia and minimise the associated micro- and macrovascular complications of diabetes." (PMID 18694484, 2008). "Virtually, all forms of diabetes mellitus are caused by a deficiency of insulin secretion or by a combination of insulin resistance and inadequate insulin secretion." (PMID 17892543, 2007). "Insulin therapy changed diabetes from a rapidly fatal disease to a chronic disease associated with significant secondary complications, such as renal failure, neuropathy, cardiovascular disease, and retinopathy." (PMID 17201925, 2007). "This, in turn, suggests that reducing visceral fat is crucial to improving insulin sensitivity and preventing diabetes in high-risk individuals." (PMID 17479164, 2007). "Weight loss has been shown to improve insulin sensitivity and prevent or delay progression to diabetes." (PMID 17479164, 2007). "Overt diabetes is preceded by an inflammatory islet infiltration, known as insulitis, that results in the targeted deletion of insulin-producing β cells and subsequent loss of glucose homeostasis." (PMID 17254331, 2007). "The natural progression of diabetes involves increasing insulin resistance and loss of pancreatic β-cell function, and antidiabetes therapies that trigger insulin secretion therefore fail over time." (PMID 17697384, 2007). "Light to moderate intake is associated with improved insulin sensitivity and with a lower risk of diabetes." (PMID 17653076, 2007). "Diabetes mellitus is a disease of abnormal glucose metabolism resulting in hyperglycemia due to either a deficiency of insulin secretion or insulin resistance or both." (PMID 23675048, 2007). "It is well documented that insulin can prevent, or revert, a number of outcomes caused by experimental diabetes." (PMID 17144912, 2006). "Dysregulation of insulin function and glucose metabolism is the hallmark of diabetes and the fact that a low-carbohydrate diet can significantly improve this aspect of metabolism is noteworthy." (PMID 16403234, 2006).
diabetes (continued). "Insulin was used in approximately 12% of patients with type 2 diabetes and was associated with approximately three times higher expenditure on diabetes testing supplies compared to patients on oral anti-diabetic medications." (PMID 17164006, 2006). "In our study, most LMQs/OEQs were used to evaluate knowledge related to diagnosis (e.g. ketoacidosis, pernicious anaemia, hypoglycemia), diagnostic procedure (e.g. potassium test) and therapy (e.g. metformin, insulin) in the key feature cases." (PMID 17032439, 2006). "The Rapid Assessment Protocol for Insulin Access was developed to provide a situational analysis of Type 1 diabetes, in order to make recommendations to the national Ministries of Health and Diabetes Associations." (PMID 16504123, 2006). "A longer history of diabetes was associated with increased use of oral medications and insulin therapy." (PMID 17164006, 2006). "Diabetes mellitus is a chronic clinical syndrome caused by insulin deficiency (defects of insulin secretion and/or action) that causes a set of metabolic abnormalities involving the metabolism of glucose, lipids, protein and other substances." (PMID 17086304, 2006). "Diabetes mellitus is a chronic disease caused by inherited or acquired deficiency in production of insulin by the pancreas or by the ineffectiveness of the insulin produced." (PMID 15703077, 2005). "Humans lacking a functional IPF1 allele have pancreatic agenesis, whereas humans heterozygous for the same variant develop early onset, insulin deficient diabetes (Maturity Onset Diabetes of the Young, MODY4)." (PMID 16229747, 2005). "Patients diagnosed with MI were more likely to have underlying insulin-requiring diabetes mellitus and peripheral vascular disease than were those patients without MI." (PMID 16280062, 2005). "Diabetes mellitus is a genetically determined metabolic disorder associated with absolute or relative impairment of insulin and in complete clinical manifestation is characterized by metabolic affections, vascular and neuropathic complications." (PMID 16446919, 2005). "Diabetes mellitus is syndrome, initially characterized by a loss of glucose homeostasis resulting from defects in insulin secretion, insulin action both resulting impaired metabolism of glucose and other energy- yielding fuels such as lipids and protein." (PMID 15969768, 2005). "Patients with high blood pressure and associated impaired glucose tolerance or overt diabetes mellitus type 2, as a group, are insulin resistant, glucose intolerant, hyperinsulinemic, dyslipidemic and with evidence of endothelial dysfunction." (PMID 15461784, 2004). "Body size, diabetes mellitus, and insulin resistance have been linked to chromosome 11; this region also contains several candidate genes, including insulin (OMIM 17673), SHIP2 (OMIM 600829), and the uncoupling protein 2 (OMIM 601693)." (PMID 14975167, 2003). "Diabetes knowledge was significantly associated with age [70–79 years: p = 0.012, above 80: p = 0.007], educational status [high school: p = 0.007, college/university: p < 0.001], and medication type [the presence of insulin in the regimen: p = 0.009]." (PMID 41311517, 2026). "Our goal was to determine whether early changes in lipid and glycemic profiles are linked to diabetes pathophysiology and related alterations in insulin secretion, action and metabolism." (PMID 41133433, 2026). "This case highlights the importance of keeping neonatal diabetes in mind for preterm, growth-restricted infants with persistent severe hyperglycemia requiring insulin after exclusion of secondary causes, and also to master the details of practical safety considerations for insulin use in early life." (PMID 42051816, 2026).